ABCG2 (ATP binding cassette subfamily G member 2 (JR blood group))
Diseases named in the same sentence as ABCG2 in open-access papers (continued):
Sharing a sentence is not in itself a finding about the gene and the disease.
cancer (continued). "Although the drug transporters ABCG2, ABCB1 and ABCC1 have been majorly implicated in cancer drug resistance, recent studies have associated ABCC3 with multi drug resistance and poor clinical response." (PMID 27171227, 2016). "Further investigation of the kinetic processes involving ABCG2 will refine our understanding of the functional consequences of ABCG2 activity in cancer cells and potentially inspire novel chemotherapeutic approaches." (PMID 27851764, 2016). "In order to determine the reversal effect of osimertinib on ABCG2-mediated MDR in ABCG2-overexpressing human cancer cells, we used the parental NCI-H460 cell line and the drug-selective NCI-H460/MX20 cell line." (PMID 27649127, 2016). "The data on the methylation patterns of ABCB1, ABCC1 and ABCG2 provided in the present study will help in selecting appropriate cancer cell lines for investigating the mode of action and/or testing the efficacy of (epigenetic) anticancer drugs." (PMID 27689338, 2016). "ABCG2 has been shown to be up-regulated in many cancers and to contribute to a multidrug resistance phenotype by transporting chemotherapeutic agents out of the cell." (PMID 27257141, 2016). "Although SP+ cells were showed to be more tumorigenic when compared to SP- cells, ABCG2+ and ABCG2- cancer cells were shown to be similar." (PMID 27766946, 2016). "Most importantly, the forced expression of Piwil2 led to a clear upregulation of ALDH, MSCA-1, and ABCG2, three common markers of cancer stem-like cells, as detected by FACS, and a significant LD50 increase of cisplatin, as determined by a CCK8 assay." (PMID 27602489, 2016). "Recent reports have shown that the chromatin-remodelling proteins have an impact on ABCG2 expression in several carcinoma cell lines." (PMID 27171227, 2016). "The device was further used to examine tumor heterogeneity such as morphology, growth rate, anti-cancer drug tolerance as well as adenosine triphosphate-binding cassette (ABC) transporter ABCG2 protein expression level." (PMID 26149707, 2015). "In this study, we sought to investigate the potency of FL118 versus irinotecan or its active metabolite, SN-38, in both in vitro and in vivo models of human cancer with high ABCG2 activity." (PMID 25928015, 2015). "Other than ABCB1, ABCG2 is a high-capacity transporter widely expressed in drug resistant cancer cells." (PMID 26431273, 2015). "To date, sixteen members have been identified, but only three major ABC drug transporters, including ABCB1 (P-glycoprotein), ABCC1 (multidrug resistance protein 1, MRP1) and ABCG2 (BCRP), are thought to affect cancer chemosensitivity." (PMID 26431273, 2015). "Our findings expand the uniqueness of FL118 and support continued development of FL118 as an attractive therapeutic option for patients with drug-refractory cancers resulting from high expression of ABCG2." (PMID 25928015, 2015). "Among various subfamilies, MDR1/ABCB1, MRP1/ABCC1, and BCRP/ABCG2 are primarily involved in anti-cancer resistance." (PMID 25853126, 2015). "The ABCG2 multidrug transporter has a role in xenobiotic transport and cancer drug resistance, uric acid transport, and was identified as the junior blood group component." (PMID 27239515, 2015). "ABCG2 has previously been found to play an important role in chemotherapy failure and migration/invasion in a variety of cancers, including colorectal, esophageal, and head and neck." (PMID 26517090, 2015). "With increasing understanding of the mechanisms of RNAi, siRNA has been proposed as an effective approach to specifically silence ABCG2 in cancer cells." (PMID 26575421, 2015). "The phenotype of SP cells is characterized by high expression of breast cancer-resistant protein-1 (BCRP1 or ABCG2), one of ATP-binding cassette (ABC) transporters, which is associated with multidrug resistance in many cancers by pumping out the drugs." (PMID 25951238, 2015).
cancer (continued). "Development of ABCG2 inhibitors can be used in combination with anticancer drugs to block the drug secretion from cancer cells." (PMID 26712767, 2015). "Sox2 has also been implicated in conveying chemoresistance to cancer stem cell-like cells in other cancers through ABCG2 expression levels." (PMID 25889105, 2015). "We also assessed the efficacy of FL118 in two distinct in vivo xenograft models of ABCG2-mediated drug-resistant cancer." (PMID 25928015, 2015). "The three major ABC-transporters associated with DR in human oncology are ABCB1 or P-gp, ABCC1 or MRP1, and ABCG2 or BCRP, and have been demonstrated in canine cell lines, healthy dogs and dogs with cancer." (PMID 29061939, 2015). "Here, we found that ceritinib remarkably enhanced the efficacy of chemotherapeutic drugs in ABCB1 or ABCG2 over-expressing cancer cells in vitro and in vivo." (PMID 26556876, 2015). "Two of the three groups that initially isolated ABCG2 did so while investigating resistance to anti-cancer agents that had developed in cell culture." (PMID 26714461, 2015). "The ATP-binding cassette (ABC) multidrug transporters such as ABCB1 (MDR1/P-glycoprotein), ABCC1 (MRP1) and ABCG2 (BCRP/MXR) are considered to be accountable for the majority of drug efflux in human cancers." (PMID 26515463, 2015). "Cancer cell lines adapted to the aurora kinase inhibitor AZD1152 had been shown to express high levels of ABCG2 and to be cross-resistant to tozasertib." (PMID 26415506, 2015). "Taken together, these results suggested that SOX4 functions to modulate cancer proliferation by regulation of cell cycle, and inhibit cancer cell sensitivity to therapeutic drug via upregulation of ABCG2." (PMID 26583330, 2015). "Recently, ABCG2 has been recognized as a molecular marker for the side population (SP) cells, these are putative cancer stem cell CSC population." (PMID 26515463, 2015). "Next, we determined antitumor activity of FL118 versus irinotecan in HC116-SN50 and H460 xenograft models of ABCG2-mediated drug-resistant cancer." (PMID 25928015, 2015). "The RNA levels of two ATP-binding cassette transmembrane proteins (ABC), ABCG2 (known as breast cancer resistance protein) and ABCB1, were dramatically up-regulated in the irinotecan-resistant cells." (PMID 25973791, 2015). "More recently, RNA interference (RNAi) has been used to knock down ABCG2 expression in cell culture and restore therapeutic benefit to anti-cancer agents that are ABCG2 substrates." (PMID 26714461, 2015). "This phenomenon is especially important in oncology, where superfamily member ABCG2 (also called BCRP – breast cancer resistance protein) is known to interact with dozens of anti-cancer agents that are ABCG2 substrates." (PMID 26714461, 2015). "In a murine model system, combination treatment of A-803467 (35 mg/kg) and topotecan (3 mg/kg) significantly inhibited the tumor growth in mice xenografted with ABCG2-overexpressing cancer cells." (PMID 26515463, 2015). "ABCG2 is responsible for the “side population” (SP) phenotype, frequently used in the identification and isolation of cancer stem cells (CSCs)." (PMID 26515463, 2015). "ABCG2 mRNA were statistically significantly lower in cancer tissue both compared to levels in unaffected tissue from the same person and compared to levels in tissue from healthy controls (all p<0.0001)." (PMID 25793771, 2015). "Several research groups have attempted to identify anti-cancer agents that are poor substrates for ABCG2." (PMID 26714461, 2015). "Completely eradicating cancer stem cells by overcoming the resistance to chemotherapy, mediated by ABCG2, would be a new targeted therapeutic strategy." (PMID 26515463, 2015). "BCRP/ABCG2 emerged as an important multidrug resistance protein, because it confers resistance to several classes of cancer chemotherapeutic agents and to a number of novel molecularly-targeted therapeutics such as tyrosine kinase inhibitors." (PMID 26536031, 2015).
cancer (continued). "ABCG2 expression reduced cancer cell sensitivity to tozasertib and the cytotoxic ABCG2 substrate mitoxantrone." (PMID 26415506, 2015). "As an important multidrug resistance transporter, ABCG2 has the capability to promote the efflux of various chemotherapy drugs contributing to cancer cell resistance." (PMID 26064420, 2015). "The mechanisms that are involved in MDR include the overexpression of mutispecific ATP-dependent drug efflux pumps, including P-gp, MRP1 and BCRP (ABCG2), which reduce the available concentration of the drug for the cancer cells." (PMID 24959278, 2014). "Among ABC transporter family, three of them, ABCB1 (P-glycoprotein/Pgp), ABCC1 (multidrug resistance protein 1/MRP1) and ABCG2 (breast cancer resistance protein /MXR/BCRP) appear to play an important role in the development of MDR in cancer cells." (PMID 24653706, 2014). "ABCG2 expression provides an early prediction of the clinical outcome of cancers, which can be used to improve the clinical management of gastric cancer patients." (PMID 25474134, 2014). "In conclusion, this suggests that the ABCG2 protein is an appealing therapeutic target, and inhibiting its mediated secretion or decreasing its expression level in cancer cells constitute potential strategies to overcome chemoresistance." (PMID 25474134, 2014). "Completely eliminating cancer stem cells by overcoming the resistance to chemotherapy mediated by ABCG2 would be a new therapeutic target." (PMID 25436978, 2014). "The tumor cells showed strong ABCG2 staining in the invasive front of cancer nests and the intensity in peripheral zone was stronger than the center zone." (PMID 24804195, 2014). "In chemotherapy for MDR cancer, inhibition of ABCG2 is expected to enhance the efficacy of the anti-cancer drug treatment." (PMID 25111504, 2014). "siRNA-mediated knockdown of snoRA42 in CD133+ cells led to a significant decrease in transcript levels of the genes, including Oct4, Nanog, Sox2, Notch1, Smo, and ABCG2 compared to scrambled siRNA-treated CD133+ cancer cells." (PMID 24886050, 2014). "Compared to the expression pattern of Ki67, we also noticed that most ABCG2-positive cells also had positive staining with Ki-67 and mainly located in the periphery of cribriform cancer nests and in both periphery and central zones of solid cancer nests." (PMID 24804195, 2014). "The characteristic of SP cells to rapidly extrude Hoechst 33342 is based on the expression of ABCG2/BCRP1, a breast cancer resistance protein (BCRP) of the ATP-binding cassette (ABC) transporter family." (PMID 24418020, 2014). "We concentrated in particular on studying the role of FOXM1 in regulating the expression of ABCG2 because ABCG2, also known as breast cancer resistance protein, belongs to the ATP-binding cassette family." (PMID 25213081, 2014). "The next natural drug candidate, fumitremorgin C at micromolar concentrations inhibited expression of the breast cancer resistant protein (BCRP/ABCG2) that mediates transport of chemotherapeutic agents." (PMID 24595456, 2014). "High levels of breast cancer resistance protein (ABCG2) gene are expressed in the surface membrane of MDR cancer cells, where it transports anti-cancer drugs including doxorubicin, mitoxantrone, topotecan, and daunorubicin." (PMID 25111504, 2014). "Conversely, ABCG2 is found to be overexpressed in SP stem cells isolated form bone marrow and a number of established cancer cell lines as well as tumor samples." (PMID 24804195, 2014). "Of interest is the observation that ABCG2 has been considered as a determinant of side population (SP) cells which are highly enriched in cancer stem cells (CSCs), and appears to play a critical role in the resistance of CSCs." (PMID 25436978, 2014). "ABCG2 is an important member of the ABC- transporter family, which functions as pumps to extrude anticancer drugs from cancer cells, by this means causing MDR in cancer patients." (PMID 25587329, 2014).
cancer (continued). "Breast cancer resistance protein (ABCG2), a member of the ATP-binding cassette transporters has been identified as a major determinant of multidrug resistance (MDR) in cancer cells, but ABC transporter inhibition has limited therapeutic value in vivo." (PMID 25111504, 2014). "Cluster analysis evaluating a subset of drug transporters including cancer-stem cell markers such as ABCG2 is suggested for further studies on the significance of drug transporters for HNSCC disease." (PMID 25275603, 2014). "Accordingly, identifying an effective TKI that can specifically inhibit or downregulate ABCG2 would dramatically accelerate the development of reversal agents for circumventing ABCG2-mediated MDR in cancer chemotherapy." (PMID 25436978, 2014). "Overall, the results indicate that cell populations that are positive for the putative cancer stem cell markers ABCG2 and Bmi-1 can occur with increased density in malignant or oral potentially malignant lesions, and cell lines derived from them." (PMID 24415717, 2014). "Elevated expression of the drug efflux transporter ABCG2 seems to correlate with multidrug resistance of cancer cells." (PMID 25587329, 2014). "In solid pattern, the myoepithelial cells were diffusely positive for ABCG2, and the highest intensity of ABCG2 staining was found focally in both periphery and center of cancer nests." (PMID 24804195, 2014). "ABCG1, ABCG4, ABCG5, and ABCG8 are involved in the ATP-dependent translocation of steroids and lipids, while ABCG2 has been identified as a multidrug transporter that confers resistance on cancer cells." (PMID 25505559, 2013). "Then, the dye-effluxing side population cells expressing ABCG2, an ATP-binding cassette half-transporter, were isolated as cancer stem cells." (PMID 24039918, 2013). "ABCG2 is known to mediate the efflux of gefitinib (Iressa®) from cancer cells, and its expression is regulated by NRF2 and the EGFR-tyrosine kinase cascade." (PMID 24040073, 2013). "Art was able to reverse drug resistance by reducing ABCG2 expression and increasing the anticancer drug concentration in the cancer cells." (PMID 24179544, 2013). "ABCG2 was firstly studied as a stem cell marker in bone marrow and its expression was subsequently detected in various cancers." (PMID 24194752, 2013). "Overexpression of ABCG2 represents an important mechanism for multidrug resistance where it significantly increases drug sensitivity in cancer cells." (PMID 24339958, 2013). "EGFR TKI gefitinib was demonstrated as a potential substrate for BCRP/ABCG2, and combinatory treatment with gefitinib was also found to overcome the BCRP/ABCG2-mediated resistance to some anti-cancer drugs." (PMID 24391798, 2013). "Overexpression of the ABCG2 gene is frequently observed in cancer cell lines selected with chemotherapeutic drugs." (PMID 24358977, 2013). "Breast cancer resistance protein (BCRP), encoded by ABCG2, is another drug efflux transporter that has been shown to play a role in resistance to various cancer therapeutics." (PMID 23524533, 2013). "In cancer cells, a high expression of ABCG2 prevents the intracellular accumulation of anticancer drugs, which results in drug resistance." (PMID 24179544, 2013). "Some signaling pathways, such as notch, CXCL12-CXCR4, Oct4-TCL1-AKT, PTEN/P13K/Akt, β-catenin/Tcf, AhR, and HIF-2α with TGF-β/Smad2 are related to the ABCG2 status as a marker of stem cells or stem-like cancer cells." (PMID 24312054, 2013). "It has been demonstrated that ABCG2 is one of the most important genes for the chemoresistance of cancer stem cells." (PMID 24223665, 2013). "The ABCG2 gene was identified as a potent ‘de-toxification’ transporter for tyrosine kinase inhibitors in cancer cells." (PMID 23467750, 2013). "ABCB1 (also known as P-glycoprotein/P-gp), ABCC (also known as multidrug resistance protein/MRP) subfamily and ABCG2 (also known as breast cancer resistance protein/BCRP) are considered major players in the development of MDR in cancer cells." (PMID 24069321, 2013).
cancer (continued). "In the present study, however, the presence of AR was found to increase cancer cell chemoresistance and ABCG2 expression." (PMID 23599788, 2013). "Upregulation of ABCG2 significantly enhanced proliferation while knockdown of this gene tremendously inhibited the growth of highly proliferative ABCG2 positive cancer cells." (PMID 24194752, 2013). "Art was able to reverse the drug resistance by reducing ABCG2 expression and increasing the anticancer drug concentration in the cancer cells." (PMID 24179544, 2013). "Collectively, these results suggest that the anti-cancer activity of sorafenib was attenuated at least in part by BCRP/ABCG2-mediated drug efflux in HCC cells." (PMID 24391798, 2013). "The use of the tyrosine kinase inhibitor imatinib has been shown to overcome cancer drug resistance via ABCG2, whereas the efflux function is inhibited by tyrosine kinase inhibitors." (PMID 23467750, 2013). "Using flow cytometry, we studied the individual expression of EpCAM, CD44, CD24 and ABCG2 and also studied the co-expression of EpCAM with other three putative cancer stem cell markers." (PMID 22328825, 2012). "It has been demonstrated that ABCG2 is the primary contributor to the SP phenotype in several cancer cell lines including A549." (PMID 22768056, 2012). "In contradistinction to IAs, topotecan was neither detected in lysosomes of cancer cells (MCF-7) nor in lysosomes of normal breast epithelial cells (MCF-10A), but accumulated exclusively in ABCG2-rich EVs of MDR cancer cells (MCF-7/MR)." (PMID 22530032, 2012). "ABCG2 is an efflux transporter commonly found to overexpress in multidrug resistant (MDR) cancer cells." (PMID 22778999, 2012). "MiR-328 has been shown to negatively regulate the expression of ABCG2 in human cancer cells, while miR-199a-3p has been shown to induce cell cycle arrest, reduce invasion, and increase doxorubicin sensitivity by negatively regulating mTOR and c-Met." (PMID 23176396, 2012). "ABCG2 is overexpressed in tumors, cancer cell lines and in a subpopulation of stem cells: the side populations, conferring multidrug resistance." (PMID 22952907, 2012). "ABCG2 overexpression in the plasma membrane of malignant tumors that mediates the extrusion of multiple anticancer drugs from the tumor cells can decrease both the efficacy and selectivity of MDR type drugs." (PMID 22530032, 2012). "ABCG2 is originally identified in anticancer drug-resistant human cancer cell lines by in vitro selection." (PMID 22870247, 2012). "MiR-328 has an important role in maintaining cancer stem-like SP phenotype by directly targets ABCG2 and MMP16." (PMID 22453125, 2012). "Accumulating evidence indicates that ABCG2 plays a particularly important role in regulating the cellular accumulation of porphyrin derivatives in cancer cells, and thereby affects the efficacy of PDD and PDT." (PMID 23189181, 2012). "To assess the activity of ABCG2 in cancer cell lines, we performed a functional assay using the Hoechst 33342 test." (PMID 23153066, 2012). "Aside from overexpression in multidrug-resistant cancer cells, ABCG2 is also widely expressed in a variety of normal tissues including in the epithelium of the small intestine, the liver canalicular membrane and ducts and lobules of the breast." (PMID 22870247, 2012). "Overexpression of ABCG2 in cancer cell lines in vitro has been shown to confer MDR to a variety of anticancer drugs including mitoxantrone, irinotecan, methotrexate, flavopiridol, and anthracyclines." (PMID 22778999, 2012). "The ABCG2 protein was observed in a wide variety of tumors and shown to be involved in the cancer cells resistance to many chemotherapeutic agents." (PMID 23153066, 2012). "Recently, it was reported that cancer cells with ABCG2-overexpressing had obvious change in endogenous JNK activity." (PMID 22870247, 2012).